PDX1 (pancreatic and duodenal homeobox 1)
Diseases named in the same sentence as PDX1 in open-access papers (continued):
Sharing a sentence is not in itself a finding about the gene and the disease.
diabetes (continued). "Understanding the signaling cues converging on Pdx1 and modulating its activity is therefore an attractive approach in diabetes treatment." (PMID 22509401, 2012). "Haploinsufficiency for FoxO1 resulted in an increase of β cells and rescued both IRS-2 knockout mice and Pdk-1 knockout mice from diabetes via restoration of Pdx1 expression in β cells." (PMID 22384192, 2012). "Given its potential role in metabolic regulation, full insights into the function of PDX1 in PCa could contribute to improved treatment and prevention strategies, particularly for men with PCa and comorbidities such as obesity and diabetes." (PMID 41955005, 2026). "In summary, we identified variants in BLK, CEL, KLF11, PDX1, and PAX4 that may contribute to various forms of diabetes, including rare MODY subtypes." (PMID 41153735, 2025). "PDX-1, a transcription factor critical for pancreatic development, islet neogenesis, and the maintenance of mature β-cell function, represents a promising therapeutic target for reversing diabetes." (PMID 40530879, 2025). "Intestinal endocrine progenitor cells from mice have the potential to be converted into insulin-secreting cells by inhibiting Foxo one or stimulating the expression of Pdx1, MafA, and Ngn3, and can be used as a complementary source in diabetes transplantation therapy." (PMID 40926989, 2025). "Hereditary forms of diabetes also include rare monogenic variants such as MODY (Maturity-Onset Diabetes of the Young), which follows an autosomal dominant inheritance pattern caused by specific mutations in genes such as HNF4A, GCK, HNF1A, HNF1B, PDX1, and NEUROD1." (PMID 40647303, 2025). "Both lipid-free and lipid-associated forms of apoA-I and apoA-II increase insulin synthesis and glucose-stimulated insulin secretion by upregulating the expression of Pdx1, thereby preserving β-cell function and reducing the harmful effects of activated T-cells in diabetes." (PMID 40405966, 2025). "Many molecules essential to islet function—including CD36 (regulates β-cell response to hyperglycemia and glucolipotoxicity), insulin receptor substrates IRS1 and IRS2, glucose transporters GLUT2, PPARG, and pancreatic and duodenal homeobox 1 (PDX1)—play key roles in the pathogenesis of diabetes." (PMID 41488148, 2025). "Another DNMTi drug called procainamide is known to partially inhibit the DNMT1 enzyme, and it protects against diabetes in mice with a deficiency in the unconventional prefoldin RPB5 interactor (URI), by decreasing PDX1 methylation levels and restoring PDX1 expression." (PMID 41007838, 2025). "However, low levels of Pdx1 accompany IPCs’ dysfunction in experimental models of glucotoxicity and diabetes." (PMID 38304198, 2024). "pdx1 mutant zebrafish constitute a valuable complement to rodent and other mammalian models of DR, in particular for research into the mechanistic interplay of diabetes with vascular and neuroretinal disease." (PMID 38279951, 2024). "PDX1 is characterized by a mild form of diabetes and can usually be treated with OAD." (PMID 39511990, 2024). "Previous studies have also shown a decrease in the expression of MafA and PDX1 in diabetes." (PMID 39238175, 2024). "As background, in 2015, a patient with a homozygous mutation in PDX1 c.527G>A(p.Arg176Gln) whose main phenotype was diabetes was reported, without registering pancreatic agenesis." (PMID 37417678, 2023). "A polysaccharide purified from Hovenia dulcis was found to ameliorate type 1 diabetes mellitus (T1DM) by up-regulating PDX-1, activating and up-regulating IRS2 expression, and regulating apoptosis and regeneration of islet β-cells to recover islet β-cell function injury in T1DM rats." (PMID 37894615, 2023). "Additionally, conditional deletion of Pdx1 in 80% of mature β‐cells in an inducible conditional knockout model induces diabetes by switching the identity of β‐cells to an α‐cell‐like phenotype." (PMID 37568265, 2023).
diabetes (continued). "For example, the antiarrhythmic drug procainamide, which also acts as an inhibitor of DNMT1, protects against diabetes by restoring the expression of the homeobox PDX1 (Pancreatic and duodenal homeobox 1) gene via a decrease in its methylation levels in β cells." (PMID 37626900, 2023). "Altered PDX1 and Hnf4-α function in humans has been associated with Maturity Onset Diabetes of the Young, a non-obese form of diabetes that can be mistaken for type 1 diabetes." (PMID 38348016, 2023). "The PDX-1 inactivation of the β-cells leads to diabetes in mice." (PMID 36246063, 2022). "Mutations in the PDX1 gene are correlated with many pancreatic dysfunctions, including pancreatic agenesis (homozygous mutation) and MODY4 (heterozygous mutation), while in other types of diabetes, PDX1 expression is reduced." (PMID 36589234, 2022). "Therefore, PDX-1 can be used as a potential target for the clinical treatment of diabetes, and a treatment strategy based on PDX-1 has great clinical application prospects." (PMID 36551213, 2022). "Importantly, sQTLs also affected genes that harbor variants that cause monogenic diabetes (KCNK16, ABCC8, PDX1) or influence T2D risk (THADA, PAM) as well as genes that play a role in T1D pathogenesis (ICA1, PTPRN2, HLA-B)." (PMID 36109769, 2022). "Thus, promoting PDX-1 expression can be an effective strategy to ameliorate β-cell dysfunction and diabetes progression, making PDX-1 a new target for developing anti-diabetic drugs." (PMID 36551213, 2022). "Here, PDX-1 and MafA were markedly downregulated following diabetes establishment in rats." (PMID 35656076, 2022). "Finally, we provide a report on the efficacy of PDX1 administration to support increased endocrine pancreatic regeneration in STZ mouse model of diabetes." (PMID 35186929, 2022). "Ros-dependent mechanisms that reduce Pdx1 levels and activity during diabetes." (PMID 36187092, 2022). "NeuroD (a factor downstream of PDX-1) and betacellulin (Btc) completely reversed diabetes in mice." (PMID 36551213, 2022). "Therefore, PDX-1-targeted therapy based on the relevant mechanism of PDX-1 provides a direction for treating diabetes." (PMID 36551213, 2022). "Studies on the role of PDX-1 in reversing diabetes are on the increase." (PMID 36551213, 2022). "Overexpression of Pdx1 in liver cells by CRISPR/Cas9-mediated TGA system (used with dgRNA that deactivates Cas9) led to their transdifferentiation into insulin-secreting cells in a mouse STZ-induced T1D model of diabetes." (PMID 36246880, 2022). "DA-1241, a novel small-molecule G protein-coupled receptor 119 agonist, can preserve pancreatic functions by suppressing ER stress and increasing the expression of PDX-1; it may be a promising drug for treating diabetes." (PMID 36551213, 2022). "Therefore, alternative approaches to treat diabetes largely depend on knowledge of PDX1 regulation, its interaction with other transcription factors, and its role in obtaining β-cells through differentiation and transdifferentiation protocols." (PMID 36589234, 2022). "Additionally, beta-cell specific Pdx1 deletion increases glucagon and somatostatin positive cells at the expense of insulin positive cells resulting in diabetes." (PMID 36187092, 2022). "Finally, we investigated the possibility to induce pancreatic β-cell regeneration in a mouse model of diabetes (i.e. the STZ mouse) by administration of PDX1." (PMID 35186929, 2022). "Deletion of Pdx1 in β-cells induces insulin-secretion disorders and diabetes." (PMID 34066196, 2021). "In support of this idea, the selective, inducible inhibition of IKK/NF-κB signaling in pancreatic β-cells could induce bona fide diabetes in pre-diabetic adult Pdx1+/− mice." (PMID 33795639, 2021). "PDX1 is a key transcriptional factor that maintains pancreatic β-cell survival and function, which is important for maintaining the stability of cell function and inhibiting the occurrence and development of diabetes." (PMID 34699323, 2021).
diabetes (continued). "In addition, Pdx1+/−/NemoΔPanc mice developed typical clinical signs of diabetes like polydipsia, polyuria and reduction of body weight." (PMID 31682591, 2020). "The overexpression of PDX1 and MafA successfully reprogrammed alpha-cells into beta-cells in vitro and in vivo, providing a significant restoration of islet function and delaying the onset of diabetes." (PMID 32708678, 2020). "We reported a case of neonatal diabetes mellitus due to novel homozygous mutation in the PDX1 gene without exocrine pancreas manifestations." (PMID 31366392, 2019). "Furthermore, these chromatin marks are reversed after treatment of the newborn rats with a peptide that counters the propensity toward diabetes, consistent with a role for these chromatin modifications in PDX1 expression and thus beta cell failure." (PMID 29642537, 2018). "Since diabetes is a common disease that could be treated with stem cell-derived tissues, we chose to focus on pancreas development by targeting the PDX1 gene." (PMID 29234093, 2017). "Thus, with pdx1 mutant zebrafish, pharmacologic effects and toxicities of new diabetes drug candidates can be evaluated at relatively low cost in a vertebrate whole-animal model before moving on to costly and labor-intensive mammalian studies." (PMID 26384018, 2015). "Interestingly, treatment with a GLP-1 analog in the first week of life reverts the epigenetic landscape at the Pdx1 gene locus to normal and rescues the diabetes phenotype." (PMID 24257104, 2013). "This study demonstrates that recessive PDX1 mutations are a rare but important cause of isolated permanent neonatal diabetes in patients without pancreatic hypoplasia/agenesis." (PMID 23320570, 2013). "Hopefully, the identification of other novel natural products that significantly modulate insulin and/or pdx1 promoter activity will point to new methods of controlling beta-cell function and fate and eventually to new diabetes therapeutics based on the lead structures of these natural products." (PMID 20886041, 2010). "Additionally, heterozygous parents of individuals with neonatal diabetes due to recessive PDX1 variants do not consistently have diabetes." (PMID 40779032, 2025). "Similarly, mutations of PDX1 gene (MODY4), which plays a crucial role in β-cell differentiation and function, are also associated with neonatal diabetes and T2DM, as well as ketosis-prone diabetes (KPD)." (PMID 39201476, 2024). "Given the influential role of Pdx1 in islet ontogeny and β cell function, as well as the control Pdx1 has on the transcriptional properties to maintain β cell identity, understanding ways in which Pdx1 transcriptional activity is modulated is paramount to define its role in diabetes pathogenesis." (PMID 37838950, 2023). "Research on the relationship between PDX-1 and diabetes has gained much attention because of the increasing prevalence of diabetes melitus (DM)." (PMID 36551213, 2022). "However, with recent advances in translational medicine research, PDX-1 may reverse diabetes and become a valuable tool for insulin therapy strategy and an effective target of diabetes pharmacogenomics." (PMID 36551213, 2022). "Interestingly, the pancreatic duodenal homeobox factor 1 (PDX1), similar to other genes that cause monogenic diabetes of the young and T2DM, is a transcription factor essential for the development of the pancreas, and was also implicated in the control of mitophagy in pancreatic β-cells." (PMID 36465657, 2022). "Therefore, pharmacological activation of the Nrf2 pathway may alleviate diabetes by preserving Pdx1 levels." (PMID 36187092, 2022). "Zebrafish diabetes models of limited duration may elicit modest downstream pathologies as compared with effects seen with sustained genetic disruption of glucose homeostasis, as in the pdx1 mutant." (PMID 32106290, 2020).
diabetes (continued). "In support of this hypothesis, Pdx1 haploinsufficiency limits the compensatory islet hyperplastic response in different mouse models of insulin resistance and results in prominent diabetes development indicating a specific stress sensitivity of Pdx1 hemizygous β-cells." (PMID 31682591, 2020). "Upregulation of the Pdx1 gene has been observed elsewhere, in which administration of Teucrium polium extract, known to contain phenolic compounds with strong antioxidant and anti-inflammatory effects, was found to reverse the symptoms of streptozotocin-induced diabetes in rats." (PMID 32599958, 2020). "The present study aimed to determine whether we could similarly reverse diabetes in the non-obese diabetic (NOD) mouse using an adeno-associated viral vector (AAV) to deliver INS-FUR ± the β-TF Pdx1 to the livers of diabetic mice." (PMID 33023100, 2020). "Experiments performed in mutant mice have shown that while the single Pbx1 or Pdx-1 knockout mice feature pancreatic islet malformations, impaired glucose tolerance and hypoinsulinemia, the trans-heterozygous Pbx1+/−Pdx1+/− mice develop age-dependent overt diabetes mellitus." (PMID 30002646, 2018). "While the MODY4 IPF-1 P33T variant contributes to monogenic diabetes, gestational diabetes, low birth weight, miscarriages and early postnatal death, fetal undernutrition silences the transcription of Pdx1 (rat homologous of MODY4 IPF-1) via promoter DNA methylation and histone modifications." (PMID 27093067, 2016). "The analysis of PDX1 in further samples, and possibly functional studies, will strengthen the evidence for or against the role of coding variants specific to the DNA-binding domain of PDX1, where we found variants in five individuals with diabetes and none in control subjects." (PMID 21569088, 2011). "In this commentary, we summarize the roles of PDX1, MAFA, and PAX6 in determining beta cell function and diabetes development." (PMID 38844555, 2024). "Our data clarified that the infusion of IPCs in the diabetes-induced rats provoked significant over-expression of pancreatic VEGF and PDX-1 genes versus the untreated diabetic rats." (PMID 36248064, 2022). "These open chromatin regions were significantly enriched in binding sites of CUX2 and HNF6 as well as several other TFs with previously established functions in pancreatic development and links to monogenic diabetes, including HNF1B, FOXA2, and PDX1." (PMID 31883919, 2020). "Thus, reduced Pdx1 activity may define a prediabetic state that is prone for diabetes development." (PMID 31682591, 2020). "At this stage, progenitor cells typically co-express PDX1, NKX6.1, and PTF1A, failure of endocrine cell formation leads to diabetes in mice." (PMID 30425728, 2018). "Here, we developed an animal model that exhibited both diabetes and AD by crossing APP/PS1 and Pdx1+/− mice." (PMID 27406855, 2016). "Reprogramming acinar cells into insulin producing cells using adenoviral (Ad)-mediated delivery of Pdx1, Ngn3 and MafA (PNM) is an innovative approach for the treatment of diabetes." (PMID 26690959, 2015). "Future studies on the interplays among HMGA1, PDX-1, and MafA might be useful in understanding the molecular basis of clinical phenotypes in certain clinical conditions where insulin secretion becomes compromised (i.e., diabetes mellitus and other categories of glucose intolerance)." (PMID 25628604, 2014). "Given the importance of Pdx1 in β-cell function and survival, targeted manipulation of Pdx1 PTM may inform therapies in maintaining β-cell function in diabetes." (PMID 40134803, 2025). "PDX1 and MAFA transcription factors have been precisely delivered to pancreatic α-cells using AAV8 vectors, reprogramming them into cells that produce insulin and restoring normal blood glucose levels in rats with diabetes." (PMID 41226304, 2025).
diabetes (continued). "This leads to insulin resistance, pancreatic β-cell dysfunction, and reduced insulin synthesis via inhibition of pancreatic duodenal homeobox-1 (PDX-1) and glucose transporter type 2 (GLUT2), ultimately contributing to hyperglycemia and type 2 diabetes mellitus (T2DM)." (PMID 40810768, 2025). "In such cases, the onset of diabetes could arise from insufficient β cell mass and/or diminished glucose-driven activation of INS by PDX1 as a consequence of attenuated DNA binding." (PMID 36272648, 2022). "Many molecules are involved in islet function and the pathogenesis of diabetes, including CD36, glucose transporters (GLUT) 2, insulin receptor substrate (IRS) 1, IRS2, pancreatic and duodenal homeobox 1 (PDX1), and peroxisome proliferator activated receptor gamma (PPARG)." (PMID 35343389, 2022). "A handful of other mutations in the PDX1 N-terminal IDR (and one in the C-terminal IDR) have been reported in diabetic patients but are similarly unlikely to be solely causative of diabetes." (PMID 36272648, 2022). "Consistently, it was found that proteasomal degradation of p300 contributes to beta cell apoptosis in diabetes condition, while removal of Set7/9 methyltransferase and disturbance of active H3K4 histone mark in beta cells reduces Pdx1 expression and insulin secretion." (PMID 36246880, 2022). "Notably, TFs linked to mature-onset diabetes of the young [MODY, HNF4A (MODY1), PDX1 (MODY4), and KLF11 (MODY7)] gain a significant number of target genes after 2 decades, which could explain how mutations in these genes can affect beta cell structure function to cause diabetes later in life." (PMID 36197983, 2022). "Experimental diabetes was generated in mice by intraperitoneal injection of 150 mg/kg of streptozotocin (STZ, N = 10); N = 10 STZ mice also received daily intraperitoneal injections of 100 μg of human recombinant PDX1 peptide (STZ + PDX1)." (PMID 35186929, 2022). "Adenovirus-mediated Pdx1 gene therapy was also shown to reverse the symptoms of T1D in cyclophosphamide-accelerated diabetes in nonobese diabetic (CAD-NOD) mice." (PMID 36140793, 2022). "In addition, genes in the mature onset diabetes in young people (hsa04950) pathway (such as HES1, GCK, FOXA3, MAFA, HNF4A, HHEX, and PDX1) were increased in stages II to IV; these genes are related to insulin secretion and the maturation of pancreatic β-cells." (PMID 33897780, 2021). "Interestingly, many of these transcription factors (PDX1, PAX6, NKX6.1, and NKX2.2) have been shown to be regulated by long noncoding RNAs (lncRNAs) that are differentially expressed in animal models of diabetes or/and in pancreatic islets from T2D donors." (PMID 33921851, 2021). "These included several genes not previously implicated in diabetes, GIGYF1, TNRC6B and PFAS, as well as GCK, HNF1A and PDX1, known MODY genes." (PMID 34732801, 2021). "In Swiss Webster male mice, this diabetes is characterized by reduced Pdx1 expression and β cell dysfunction, in the absence of insulin resistance even in HFD-fed mice, that progresses to β cell death." (PMID 30842440, 2019). "Indeed, our previous work is consistent with this notion and has shown that reductions in SERCA2b mRNA in models of diabetes may arise instead from the loss of key transcriptional regulators such Pdx-1 and PPAR-γ, rather than through decreased transcript stability." (PMID 26086963, 2015). "Pdx1 transfected into human BM-MSC could induce IPCs and injected to diabetes mice could sustain a decline of blood glucose more than 80 d." (PMID 24885418, 2014). "Take a step further to determine whether the induced IPCs give full scope to normal physiological functions of β islet cells, mMSCs expressing a combination of PDX-1, NeuroD1, and MafA were transplanted into the livers of mice with STZ-induced diabetes." (PMID 22761608, 2012). "Ectopic overexpression of Pdx1 activates pancreatic genes in nonpancreatic cells, and these Pdx1-expressing liver cells can ameliorate streptozotocin-induced diabetes." (PMID 22611393, 2012).